LBHD2 (LBH domain containing 2)
Gene: Protein-coding gene on chromosome 14 (103,084,210 to 103,090,027, forward strand). Ensembl gene ENSG00000283071.
Homologues: Orthologues: macaque LBHD2 (93% identical), chimpanzee LBHD2 (82% identical), dog LBHD2 (65% identical), guinea pig LBHD2 (61% identical).
Diseases named in the same sentence as LBHD2 in open-access papers:
LBHD2 is named in the same sentence as 1 disease in open-access papers, as found by Europe PMC text mining. Sharing a sentence is not in itself a finding about the gene and the disease. The quoted sentences say what the papers report.
Sepsis (1 paper, 2025). Sepsis is defined as life-threatening organ dysfunction caused by a dysregulated host response to infection. "The top ten differentially expressed genes in this study include Gm29879, Lcn2, Cxcl10, Zbp1, Lbhd2, C5aR1, Cxcl10, Lbhd2, Cxcl9, and Fpr1, all of which might play a role in the pathophysiology of sepsis-induced WMI." (PMID 41584453, 2025).